SLPI (secretory leukocyte peptidase inhibitor)
Diseases named in the same sentence as SLPI in open-access papers (continued):
Sharing a sentence is not in itself a finding about the gene and the disease.
cancer (continued). "Due to the critical role of E6 oncogene in maintaining the malignant phenotype of HPV-positive cancer cells, we wondered whether SLPI could still maintain its inhibitory role in HPV E6 positive HNSCC cells." (PMID 31462893, 2019). "Reports have demonstrated that secretory leukocyte protease inhibitor (SLPI) is overexpressed in various cancers and may be a potential therapeutic strategy for the treatment of different cancers." (PMID 25954138, 2015). "SLPI is also produced in cancer tissues and upregulated under tumorigenic conditions." (PMID 25954138, 2015). "Furthermore, SLPI’s ability to modulate anti-apoptotic pathways may contribute to cancer cell survival under stress conditions." (PMID 41557653, 2026). "Furthermore, SLPI (secretory leukocyte peptidase inhibitor), which belongs to the category of ECM regulators, is currently being tested to verify whether an increased SLPI level in the sera may serve as a biomarker of cancer progression (NCT04854343)." (PMID 38255186, 2023). "SLPI were overexpressed preferentially in human patients that had lung-metastatic relapse, its poor prognosis suggests that it may be widely related to the drivers of human cancer metastasis progression." (PMID 35186034, 2022). "Importantly for this interaction, we detected SLPI inside the nucleus of cancer cells." (PMID 29312532, 2017). "Both SLPI and MMP-9 are involved in inflammation and the link between them was reported in the context of as cancer and lung diseases." (PMID 40496854, 2025). "Conversely, SLPI, WFIKKN1, WFDC2, and WFDC1 demonstrated variable prognostic effects across cancer types, suggesting context-dependent, microenvironment-driven functional duality." (PMID 40350979, 2025). "For instance, B2M, SLPI, BST2, GAPDH, S100A8, S100A9, and HMGB1, despite their beneficial roles in various infections, they contribute to cancer cell proliferation, invasiveness, reduced survival, and increased disease severity across different cancers." (PMID 38589404, 2024). "Our prostatectomy tissue analysis showed a positive relationship with AR and SLPI expression, which are basically HNPC and AR‐dependent cancers." (PMID 36812122, 2023). "Metastatic cancer cells that intravasate into the vasculature secrete Serpin Family E Member 2 (SERPINE2) and secretory leukocyte protease inhibitor (SLPI) to promote metastasis." (PMID 36046433, 2021). "HPV+ SiHa cancer cells expressed high levels of CEBPD, SLPI, and PPL mRNA relative to HFKs and HPV-C33A cancer cells." (PMID 34944802, 2021). "Many factors, including EphA2, Notch4, VE‐cadherin, SLPI, TWIST, VEGF, vimentin and HIF‐1α, are related to the formation of VM in many cancers." (PMID 33118329, 2020). "Both SLPI and P13 are co-expressed with WFCD2 and have been identified as a promoter in cancer development in various carcinomas." (PMID 28679402, 2017). "Subpopulation B consisted of 121 cells (29.1%) and showed overexpression of 13 genes, including seven cancer genes (HSPB1, ANXA1, SLPI, KRT8, KRT19, KLK7, and ABL2) and several Keratin genes (KRT8, KRT7, KRT19, and KRT6B)." (PMID 28794488, 2017). "According to our data, it can be assumed that smoking-induced SLPI expression prevents HPV infection, resulting in delayed agent-dependent cancer with poorer prognosis." (PMID 23467841, 2013). "In humans, HE4, SLPI, and several other WAP members co-locate in 20q12-13, a region frequently amplified in a variety of cancers." (PMID 23502467, 2013). "In addition, the silencing of SLPI led to a diminished viability rate in both HT29 and HCT116 cancer cells compared to NC." (PMID 36595102, 2023). "The immune histochemical sections of the HPA database showed that the protein expression of SLPI, DES, IAPP, NPY, ISG15 and HLA-DMB in normal tissue was higher than that in cancer tissue, while the protein expression of PLA2G2A in normal tissue was lower than that in cancer tissue." (PMID 36774376, 2023).
cancer (continued). "Since HPV E6 mediated multiple pathways in cancer progression, we then attempted to explore whether SLPI was also involved in Akt signaling though no relevant studies exist." (PMID 31462893, 2019). "Using RNA-seq analysis, we have identified SLPI among the top three upregulated genes in the highly tumorigenic CD24+ Mvt1 cell subset, and suggests that SLPI may play a role in the more aggressive cancers derived from CD24+ cells." (PMID 27179633, 2016). "Candidates APOA4, VDBP, A1AT/SERPINA1, and SLPI were selected for initial validation and were measured by ELISA in serum samples from 89 benign and 70 malignant ovarian cancer cases, with the latter grouped into early‐stage (FIGO I and II) and late‐stage (FIGO III and IV) cancers." (PMID 25290619, 2014).
infection (37 papers, 2006 to 2025). The state of being infected such as from the introduction of a foreign agent such as serum, vaccine, antigenic substance or organism. "These ROC curves show that the amount of SLPI is associated with bacteriuria in mice at each time point we examined from 3 hpi to 4 days post-infection (dpi) with an AUC value of 0.79 or greater." (PMID 38270443, 2024). "Serine and cysteine proteases produced by the house dust mite in asthma have been shown to cleave SLPI and may increase the susceptibility of patients with allergic inflammation to infection." (PMID 16503962, 2006). "At 24 h postinfection, 83% of wild-type mice had survived the infection, which suggest that endogenous SLPI is involved in controlling the inflammatory responseto protect the host." (PMID 40421173, 2025). "We propose that, during the active infection of the murine joint structures, the binding of B. burgdorferi with SLPI depletes the local environment of SLPI." (PMID 40392222, 2025). "While changes in SLPI expression have been associated with infections at mucosal sites, the relevance of SLPI during experimental infection is largely unexplored." (PMID 38270443, 2024). "Infection of the nasal explant with EHV-1 resulted in a significant decrease (P = 0.036) in SLPI secretion at 24 h, compared to uninfected controls." (PMID 39162558, 2024). "We found that mice respond to the introduction of UPEC in the urinary tract by upregulating SLPI within hours of infection." (PMID 38270443, 2024). "Future experiments to assess differences in uroepithelial exfoliation and use of a tissue-specific deletion of SLPI will further elucidate the cellular origins of SLPI in the urinary tract during infection." (PMID 38270443, 2024). "Taken together, these findings imply that SLPI, similar to the serpin antiprotease family, helps to resolve inflammation in the bladder following infection by limiting the mucosal damaging protease activity of NE in the urinary tract." (PMID 38270443, 2024). "We found that infection with UTI89 resulted in significantly increased secretion of SLPI protein into the culture supernatant within 2 h of infection compared to cells exposed to PBS alone (P = 0.02)." (PMID 38270443, 2024). "Our study shows that SLPI is localized to bladder epithelial cells, suggesting urine SLPI is arising, at least in part, from the bladder epithelium during infection." (PMID 38270443, 2024). "Here, we use a preclinical model of UTI to study secretory leukocyte protease inhibitor (SLPI), an antimicrobial protein, to determine how it protects the bladder against infection." (PMID 38270443, 2024). "At 6 h post infection, SLPI KO mice did, however, have significantly higher BAL fluid levels of IL-6 than that of wild type mice." (PMID 36551159, 2022). "Accordingly, SLPI exerts modulatory and protective functions in numerous human and experimental diseases, including endotoxemia, infection, psoriasis, asthma, neuro-degeneration, obesity, diabetes type 2, and cancer." (PMID 36105198, 2022). "At 24 h post infection, 83% of wild-type mice had survived the infection, whereas approximately 30% of SLPI-KO mice survived." (PMID 36551159, 2022). "The anti-inflammatory elafin and SLPI both have antimicrobial properties and contribute to the innate immune response to protect against infection." (PMID 29089928, 2017). "Increased concentrations of SLPI can be found in infection, for example, in pneumonia, whereas downregulation is triggered by interferon-gamma (IFN-γ)." (PMID 26185365, 2015). "Here, we propose a complementary mechanism whereby aggravated hypoxia during infection contributes to the reduction in SLPI concentration." (PMID 25851169, 2015). "It was previously demonstrated that SLPI inhibits the infection of HIV-1 through extracellular annexin A2, and HSV causes a sustained down-regulation of SLPI." (PMID 22927980, 2012).
infection (continued). "Our data demonstrate that supplementation of differentiated nasal epithelial cells with EGCG from the basolateral side (to eliminate direct interaction with the virus during infection) significantly increases SLPI production." (PMID 22496898, 2012). "Among serine proteinase inhibitors, SLPI is considered as "alarm proteinase inhibitor" that is upregulated during infection or inflammation to compensate for high human neutrophil elastase." (PMID 21612671, 2011). "Correspondingly, CCL20 was significantly up-regulated at 24 h, 48 h and 72 h post infection (p<0.05) and SLPI was significantly up-regulated at 48 h and 72 h post infection (p<0.05)." (PMID 19806192, 2009). "The expression of the antimicrobial peptide genes, lysozyme, CCL20 and SLPI, at 4 h, 24 h, 48 h and 72 h post infection was determined using qRT-PCR." (PMID 19806192, 2009). "We conclude that corneal inflammation and infection lead to SLPI expression based on the presence of elevated SLPI expression in S. aureus -infected and epithelial defect eyes, but not in normal control eyes." (PMID 20309414, 2009). "In LA-4 cells, infection with B. pseudomallei resulted in significant down-regulation of lysozyme and significant up-regulation of CCL20 and SLPI at 6 h and 24 h post infection compared to uninfected control cells (p<0.05)." (PMID 19806192, 2009). "On the other hand, pre-treatment with SB203580 (10 μM) resulted in significant reduction in the up-regulation of only CCL20 and SLPI genes upon B. pseudomallei KHW infection compared to controls (p<0.05)." (PMID 19806192, 2009). "Pre-incubation of the epithelial cells with BAY11-7082 (10 μM) significantly impaired the up-regulation of all three CCL20, lysozyme and SLPI genes upon B. pseudomallei KHW infection compared to untreated cell controls (p<0.05)." (PMID 19806192, 2009). "This relation to infection has been confirmed in studies showing that SLPI was also reduced in vaginal secretions in the presence of bacterial infection." (PMID 18699987, 2008). "The correlation of SLPI in place, time, and intensity withthe inflammatory process strongly supports that SLPI is upregulated as a resultof the infection and/or inflammation." (PMID 18274645, 2007). "This is supported by our findings that SLPI expression correlates in location, time, andintensity with the clinical infection." (PMID 18274645, 2007). "As the infection progresses to the anteriorsegment at 48 hours, the SLPI immunoreactivity colocalizes to the cornea." (PMID 18274645, 2007). "Interestingly, bacteriuria (UPEC in the urine) peaked 1 day after infection, long after the apex of urine SLPI levels, suggesting that SLPI is involved in the early stages of infection." (PMID 38270443, 2024). "It is not known if the presence of SLPI influences the exfoliation of the bladder epithelium during infection and increases in SLPI seen in the urine could come through enhanced exfoliation and lysis of infected cells in addition to increased secretion." (PMID 38270443, 2024). "We used an established mouse model of UTI to determine whether SLPI levels are increased in the urine following infection." (PMID 38270443, 2024). "Some of the highly expressed genes (Log2 FC > 3.5) in inverse manner during Neisseria and Borrelia like HAPLN1, MT3, PITX2, ID4, ELAFIN, SLPI, etc., could be targeted to know their relevance in favoring or resisting the infection." (PMID 38179419, 2023). "Furthermore, these cells show a short-lived increase in secreted antimicrobials including elafin, CCL5 and secretory leukocyte peptidase inhibitor (SLPI) following infection." (PMID 31156637, 2019). "Also CTSS has the potential to cleave and inactivate SLPI which further increases NE levels and facilitates bacterial colonization and infection." (PMID 26185365, 2015). "During infection, the activity of locally produced mucosal alarm antiproteases, such as elafin and secretory leukocyte peptidase inhibitor (SLPI), may add an extra edge to the host defense." (PMID 25674088, 2015).
infection (continued). "However, significant down-regulation of lysozyme was observed only at 6 h for BALB/c mice (p<0.05) while up-regulation of SLPI was observed only at 24 h post infection in BALB/c mice (p<0.05)." (PMID 19806192, 2009). "Previously, we hypothesized that SLPI plays a role in the innate immune defense of the eye in response to intraocular inflammation and infection." (PMID 20309414, 2009). "We hypothesized that SLPI plays a role in the innate immune defense of the eye in response to intraocular inflammation and infection." (PMID 18274645, 2007). "SLPI through its C terminal domain is a serine protease inhibitor and provides significant protection against neutrophil elastase, a powerful elastolytic enzyme released from neutrophils during degranulation at areas of infection and inflammation." (PMID 16503962, 2006). "Our findings define SLPI as an important innate host factor that helps to repel bacterial pathogens within the urogenital tract, demonstrate a causal role for SLPI in resolving mucosal inflammation, and imply that SLPI may directly protect from infection at other mucosal sites." (PMID 38270443, 2024). "Interestingly, CRP, AAT, and SLPI specifically inhibit the ATP (trauma)-induced release of IL-1β, while sparing the ATP-independent inflammasome activation against pathogens, which is vital in the context of severe injuries and infections." (PMID 36105198, 2022). "Therefore, SLPI's role in controlling this process on the respiratory tract may be an important homeostatic mechanism in maintaining sufficient monocyte numbers for infection and inflammation resolution." (PMID 26247039, 2015). "From a physiological standpoint, SLPI's antiapoptotic effect in monocytes may be important for optimising the removal of dying cells and bacteria as part of the inflammation resolution process and the fight against infection." (PMID 26247039, 2015). "Therefore at present the concept that a primary deficiency of SLPI initiates inflammation or infection is not well supported by the available data." (PMID 18699987, 2008). "It has been demonstrated that secretory leukocyte protease inhibitor (SLPI) prevents HPV-16 entry into cells and subsequent infection." (PMID 40565012, 2025). "For this reason, women with BV have reduced levels of an important innate immune protein, secretory leukocyte protease inhibitor (SLPI), which protects the mucosa from infection." (PMID 40428805, 2025). "We find that SLPI is increased during UTI, accelerates the clearance of bacteriuria, and upregulates genes and pathways needed to fight an infection while preventing prolonged bladder inflammation." (PMID 38270443, 2024). "Taken together, productive EHV-1 infection in non-immune horses inhibited mucosal SLPI gene expression, while SLPI secretion was delayed and likely originated from cells in the underlying tissues, which are not directly interacting with the virus during early infection." (PMID 39162558, 2024). "During experimental UTI, SLPI-deficient mice had increased NE (but not neutrophils) in their urine even before infection and long after peak neutrophil infiltration in the urine, implying that SLPI limits NE abundance during homeostasis and infection in the urinary tract." (PMID 38270443, 2024). "This points to an essential role of SLPI in early immunoregulation after EHV-1 exposure, by orchestrating the mucosal immune response toward protection from disease after infection and return to homeostasis." (PMID 39162558, 2024). "AMPs, such as cathelicidin (LL-37) and secretory leukocyte protease inhibitor (SLPI), are inhibited in CF by the overexuberant production of NE produced as a result of infection in the lung." (PMID 35408875, 2022). "SLPI also has antimicrobial and anti-inflammatory properties, but the concentration of SLPI in lung secretions in COPD varies inversely with infection and the concentration of NE." (PMID 18699987, 2008).
infection (continued). "Previous studies have confirmed that saliva contains secretory leukocyte protease inhibitor (SLPI), which can inhibit HIV-1 activity, especially in the early infection stage, that is, the body produces protease as a protective mechanism against the virus to maintain oral functions." (PMID 34925329, 2021). "Recently, it was demonstrated that exposure of human cervical epithelial cells to HSV results in a reduction in the expression of secretory leukocyte protease inhibitor (SLPI), a mediator of mucosal immunity that has been shown to inhibit HSV infection as well as infection by HIV." (PMID 22927980, 2012). "The down-regulation of endogenous SLPI expression in AGS cells by siRNA methodology did not affect the Progranulin expression independent of the infection by H. pylori." (PMID 21612671, 2011). "In order to elucidate the pathways that are involved in the regulated expression of the antimicrobial peptide genes, lysozyme, CCL20 and SLPI, LA-4 cells were pre-incubated with specific inhibitors of NF-κB and p38 MAPK pathways (BAY11-7082 and SB203580 respectively) prior to the infection process." (PMID 19806192, 2009). "These properties suggest that SLPI may be important in diseases such as bronchiectasis and COPD that are characterized by neutrophilic inflammation and infection." (PMID 18699987, 2008). "Interestingly, rises in SLPI protein found in urine and cell culture supernatants following infection are not accompanied by corresponding increases in Slpi RNA transcripts." (PMID 38270443, 2024). "It was later revealed that SLPI directly interacted with annexin A2 (A2), a PS-binding moiety, and that SLPI could disrupt the interaction between A2 and PS on the HIV-1 envelope to prevent infection in vitro." (PMID 27863502, 2016). "To determine whether SLPI has a role in inflammation and infection of the eye, where SLPI has not been described before, we investigated and quantified SLPI expression in normal and infected ocular tissues using amurine bacterial endophthalmitis model." (PMID 18274645, 2007). "An increasing body of evidence suggests that, in addition to functions in host defense against infections, the acute-phase proteins CRP, AAT, and SLPI are part of anti-inflammatory negative feed-back loops." (PMID 36105198, 2022).